ZFP36 (ZFP36 zinc finger CCCH-type)
Diseases named in the same sentence as ZFP36 in open-access papers (continued):
Sharing a sentence is not in itself a finding about the gene and the disease.
tumor (82 papers, 2014 to 2025). "Due to its ability to regulate mRNA stability and its loss of expression in various human malignancies, ZFP36 is considered a potential tumor suppressor." (PMID 40650680, 2025). "Among the aberrantly expressed genes, ZFP36 displayed the most significant association with both inflammatory pathways and tumour‐related biological behaviours." (PMID 38351596, 2024). "The modulation of tumour‐related biological behaviours by ZFP36 is associated with its capacity to bind to and disrupt pivotal regulatory factors." (PMID 38351596, 2024). "Research has shown that ZFP36 regulates tumorigenesis by destabilizing the expression of critical genes implicated in both, tumor onset and tumor progression, such as HK2, HIF1α, and c-Myc." (PMID 39026155, 2024). "Our data demonstrate that activation of lymphocyte mimicry by loss of Zfp36 is tumor cell autonomous, supporting the concept of tumor cell phenotypic plasticity." (PMID 39560993, 2024). "Where tumor development was already being driven by loss of the tumor suppressor Pten, additional loss of Zfp36 resulted in a pronounced increase in PCa progression in vivo." (PMID 39560993, 2024). "These genes were previously demonstrated to be directly regulated by ZFP36 in other studies and were associated with the development of a pro‐tumour inflammatory microenvironment." (PMID 38351596, 2024). "The results of drug sensitivity and drug resistance analysis showed that the expression of ZFP36 in tumor tissues of GC patients was associated with resistance to CGP60474 and gefitinib, and sensitivity to camptothecin, SB52334, talazopanib, and TW37." (PMID 36010886, 2022). "Associated with low expression levels of ZFP36, those coregulated genes were believed to form a positive network in tumor cell proliferation." (PMID 34805166, 2021). "These include EGR1, which is known to bind to the ZFP36 promotor and regulate a number of factors associated with tumor progression in mammary gland tumors, including FOS." (PMID 29073243, 2017). "Zfp36 loss induces tumor cell changes associated with phenotypic plasticity." (PMID 39560993, 2024). "Moreover, the analysis of tumour grade showed that lower ZFP36 expression was associated with higher tumour grade." (PMID 38351596, 2024). "Given the observed rapid disease progression and gene set enrichments following loss of Zfp36, we hypothesized that phenotypic plasticity was occurring given similar findings when loss of other tumor suppressors occur with PTEN loss." (PMID 39560993, 2024). "ZFP36 TZF mutations also increased the growth of breast cancer cells." (PMID 29426877, 2018). "More recently, ZFP36 has been linked to cancer thanks to evidences showing its down-regulated state in several tumours including CRC, and the demonstration of its ability to regulate the expression of many oncogenic targets carrying ARE sequences in their 3′ UTR." (PMID 27463018, 2016). "However, we hypothesize that, since, in general, loss of ZFP36 fosters tumor progression, in different cell contexts ZFP36 down-regulation might result from the modulation of pathways that are crucial to a specific tumor." (PMID 32784485, 2020). "However, it can be also hypothesised that, since loss of ZFP36 strongly fosters tumour progression, this event can occur in different cell contexts through the modulation of the pathways that are crucial to a specific tumour." (PMID 27463018, 2016). "This study observed that inhibition of ZFP36 expression exerted anti-tumor effects while suppressing hepatic inflammatory and lipid synthesis responses." (PMID 40650680, 2025). "Here, we confirmed that ZFP36 is biologically relevant in PCa, resulting in increased tumor progression and resistance to ARSI in PTEN-null patients and tumor models." (PMID 39560993, 2024). "The heatmap demonstrated SERPINE1 was up-regulated in tumor tissues, while the rest four genes (ZFP36, DUSP1, CAV1, and AKAP12) were down-regulated as compared to the normal group." (PMID 39165353, 2024).
tumor (continued). "The down‐regulation of ZFP36 can significantly enhance the invasion of tumour cells into the basement membrane by activating IL‐6 and MMPs in HNSCC." (PMID 38351596, 2024). "Also, we previously identified ZFP36 as a key regulator of NF-κB signaling and as such hypothesized that ZFP36 loss may drive PCa progression by creating a pro-proliferative, inflammatory tumor environment, and features of phenotypic plasticity." (PMID 39560993, 2024). "Examination of the NCI neoadjuvant ADT tumor dataset demonstrates that ZFP36 expression is not only elevated upon enzalutamide treatment, but also differs between responders and non-responders." (PMID 39560993, 2024). "In the NCI tumor dataset, we examined the correlation between ZFP36 expression and the volume of post-treatment residual tumor." (PMID 39560993, 2024). "In this study, these genes were highly expressed in GC tumor tissues, whereas ZFP36 showed the opposite expression pattern." (PMID 38388534, 2024). "In recent years, independent research groups have suggested that ZFP36 functions as a tumor suppressor since its expression is suppressed in various tumor types compared with normal tissues." (PMID 39560993, 2024). "The findings demonstrated significant inhibition of tumour‐related biological behaviour in the cells following ZFP36 overexpression." (PMID 38351596, 2024). "Our results support the idea that ZFP36 induction occurs through mTORC1 inhibition, providing novel mechanisms involved in the metformin effects on tumor growth suppression and inhibition of cancer-derived cell lines." (PMID 39026155, 2024). "We found that changing the expression level of ZFP36 can effectively affect a variety of tumour‐related biological behaviours." (PMID 38351596, 2024). "High levels of ZFP36 can also enhance the sensitivity of tumour cells to cisplatin by inhibiting BCL‐2, an anti‐apoptotic protein." (PMID 38351596, 2024). "Sustained stabilization and enhanced translation of ARE-mRNAs are features of tumor cells, which is attributable to aberrant ZFP36-mediated post-transcriptional control of gene expression in cancers." (PMID 37587140, 2023). "The functional interplay was further confirmed by the in vivo tumor xenograft experiment, which showed that BARX1 overexpression promoted tumor progression, and importantly, ZFP36 significantly attenuates BARX1-mediated tumor progression in vivo." (PMID 37587140, 2023). "According to the Pearson correlation analysis, the two DEGs, including ISG15 and ZFP36, were closely correlated with tumor-infiltrating immune cell subsets, suggesting the involvement of prognostic genes in the immune response in PCa progression." (PMID 35538543, 2022). "Except for these results, these genes not only showed very good consistent expression in tumor samples, the expression level of ZFP36 was also significantly negatively correlated with patient survival." (PMID 35693633, 2022). "ZFP36 is downregulated in the tumor compared with normal samples, and co‐expressed with JUN, JUNB, FOS, and FOSB, downregulation of which was associated with poor outcomes and BC progression." (PMID 35037412, 2022). "Compared with normal tissues, the expression of ISG15 was significantly increased in tumor tissues, whereas the expression of ZFP36 was significantly decreased." (PMID 35538543, 2022). "Consistently, ZFP36 overexpression potently inhibited tumor-induced lymphangiogenesis induced by nicotine or OTUD3 depletion, as indicated by LECs’ migration and tube formation." (PMID 34853315, 2021). "The relative mRNA ratio of human HPRT1 to mouse GAPDH47 indicated that ZFP36 strikingly decreased the proportion of colonized tumor cells in LNs." (PMID 34853315, 2021). "A20 and CH12.LX are tumor cell lines of presumed B cell origin and the two cell lines appear to have low expression of Zfp36." (PMID 34180954, 2021).
tumor (continued). "RAS-MEK signaling upstream of p38-MAPK mediates tumor cell intrinsic expression of PD-L1, partly by supressing ZFP36-dependent CD274 mRNA decay, and promotes tumor-immune evasion." (PMID 29875770, 2018). "The retarded tumor growth in Zfp36−/− mice was recovered in the TTP and WSX-1 double knockout mice, further suggesting that IL-27-dependent antitumor effect is mediated by CD8 T-cells in Zfp36−/− mice." (PMID 29021521, 2017). "In a murine mammary gland tumor model, mice deficient of TTP showed retarded tumor growth, which is in line with the increased tumor-infiltrating CD8+ T-cells of Zfp36−/− mice." (PMID 29021521, 2017). "More importantly, depletion of CD8 T-cells in Zfp36−/− mice accelerated tumor growth and increased tumor mass." (PMID 29021521, 2017). "Depletion of CD8 T-cells in Zfp36−/− mice resulted in accelerated tumor growth, demonstrating that antitumor immunity in Zfp36−/− mice depends on CD8 T-cells." (PMID 29021521, 2017). "By analyses of tumor sections stained with H&E, we observed more tumor infiltrating lymphocytes in tumors of the Zfp36−/− mice compared with other groups." (PMID 29021521, 2017). "We provide a molecular mechanism for the tumor suppressor role of ZFP36, and the first evidence for Ripoptosome assembly following ZFP36 expression." (PMID 25939870, 2015). "A growing body of literature demonstrates the ability of ZFP36 to negatively regulate mRNAs coding for oncogenes in different cellular contexts thereby exerting anti-tumor activities." (PMID 25939870, 2015). "Reduced expression of ZFP36 in HCC is correlated with advanced tumor stage and poor prognosis." (PMID 40361912, 2025). "ZFP36 is involved in the regulation of a variety of biological behaviours of tumour cells, including uncontrolled cellular proliferation in the absence of external growth signals, resistance to apoptosis, sustained angiogenesis, as well as tissue invasion and metastasis." (PMID 38351596, 2024). "ZFP36 disruption slightly increased antigen-independent activation and cytokine responses but did not enhance overall performance in vitro or in vivo in a xenograft tumor model with NSG mice." (PMID 38326511, 2024). "For this intriguing study, we look forward to future research that directly investigates the role of ZFP36 in tumor tissue and whether it presents contrasting effects on patient prognosis." (PMID 38760742, 2024). "Although the mechanism for ZFP36 regulation remains unclear, our results suggest that metformin inhibits tumor growth through ZFP36 induction via mTORC1 inhibition." (PMID 39026155, 2024). "In both breast and PCa, low ZFP36 expression is a negative prognostic indicator, and it is associated with rapid tumor progression and poor clinical outcome." (PMID 39560993, 2024). "In addition to improving control of tumor growth and response to AR inhibition, treatment of Ptenf/fZfp36f/f PCa organoids with DMAPT partially reversed the phenotypic effects of Zfp36 loss." (PMID 39560993, 2024). "ZFP36 expression is decreased in tumor tissue from CC patients." (PMID 39026155, 2024). "Despite a global increase in ZFP36 expression, the lowest levels of ZFP36 activation after treatment were observed in patients with the greatest residual tumor burden, highlighting the clear effect that functional TTP appears to be having on response to therapy." (PMID 39560993, 2024). "The gene ZFP36 also shows tumor-specific functions, but its biological roles in GC remain largely unknown." (PMID 38021154, 2023). "Research has shown that SENP3-EIF4A1 derived from exosomes could inhibit tumor growth in vivo and modulate the levels of ZFP36 ring finger protein (ZFP36) by competitively binding to miR-9-5p84." (PMID 35352001, 2022). "ZFP36 is a member of RNA-binding proteins (RBPs) increasingly appreciated as being essential for normal hematopoiesis, and it is understood to play fundamental roles in hematological malignancies by acting as oncogene or tumor suppressor." (PMID 35371979, 2022).
tumor (continued). "OTUD3 stabilized the tumor-suppressive ZFP36 protein and induced rapid mRNA decay of VEGF-C." (PMID 34853315, 2021). "Although VEGF-C transcription has been well studied, whether its mRNA decay is regulated by ZFP36 to acquire high tumor-induced lymphangiogenesis capacity remains obscure." (PMID 34853315, 2021). "Notably, previous studies demonstrated that ZFP36 played tumor-suppressive roles in animal models and human cancers." (PMID 34853315, 2021). "Additionally, exosomal SENP3-EIF4A1 was capable of inhibiting tumor growth in vivo and modulating the expression of ZFP36 by competitively binding to miR-9-5p." (PMID 32602848, 2020). "ZFP36 gene is frequently downregulated in different cancers, where, although specific mutations affecting it are not described, it seems to act as a tumor suppressor." (PMID 32784485, 2020). "Accordingly, ZFP36 expression was downregulated in tumor tissues in three large human data sets." (PMID 31717307, 2019). "Moreover, the ability to activate T cells to target tumor antigens and the clinical utility of checkpoint inhibitors raise the possibility of exploring ZFP36 inhibition to enhance tumor immunity." (PMID 29848443, 2018). "In addition, absolute numbers of CTLs were significantly increased in tumors of Zfp36−/− mice compared with tumors of other mice, when normalized against tumor mass, indicating an important role for CD8 T-cells in antitumor activity of the Zfp36−/− mice." (PMID 29021521, 2017). "Importantly, the retarded tumor growth in Zfp36−/− mice was completely relieved in TTP/WSX-1 DKO mice." (PMID 29021521, 2017). "Additionally, NEDD9 was predicted to interact directly with the zinc finger protein 36 homolog (ZFP36), a tumor suppressor gene that negatively regulates NFκB." (PMID 27078000, 2016). "In contrast, genes including KLF4 and ZFP36 exhibited differential expression dynamics by group that were not consistently echoed by their group-specific expression levels, thus undermining their prognostic value and instead being relevant predictors of the tumor biology." (PMID 40770193, 2025). "Therefore, we consider that in the human mammary gland, low expression of TTP/ZFP36 may favor tumor development as several oncogenic and inflammatory pathways would be upregulated and therefore may contribute to progression of the disease." (PMID 38274271, 2023). "In this study, proCAFs act as the initial infection-responsive population carrying ZFP36 and THBS1 programs, while iCAFs represent a later expansion phase that spatially interacts with tumor cells and consolidates stromal-immune suppression." (PMID 41194113, 2025). "Mechanistically, PLUM interacts with Polycomb Repressive Complex 2 to regulate its stability and histone methyltransferase activity, modulating the expression of tumor suppressor genes, FOXO3 and ZFP36, to activate the unfolded protein response (UPR)." (PMID 40890111, 2025). "Protein expression of ZFP36, LRP5, β-catenin and stemness factor NANOG in tumor samples was then analyzed." (PMID 40038255, 2025). "BECN1, ELAVL1, and ATG16L1 were highly expressed in tumor tissues, while NCOA4, FTH1, FTL, SNCA, TNF, ATG7, and ZFP36 showed low expression levels." (PMID 39593730, 2024). "Results showed that the regulatory factors CRNDE, EDN1, JUNB, and MAP2K1/2, ZFP36 mainly regulate differentially expressed genes (VEGFA, EGFR, PLAUR) to regulate invasion of cells, invasion of tumor, and microtubule dynamics." (PMID 38711992, 2024). "We demonstrated that BARX1 was upregulated and functioned as an oncogene, whereas ZFP36 was downregulated and acted as a suppressor in NSCLC cell lines and clinical tumor tissues." (PMID 37587140, 2023). "The single-cell transcriptome and single-cell multi-omics analyses revealed that novel tumor-related genes, such as AMIGO2, ZFP36, BTG1, and DLG5, were mainly upregulated in pituitary neuroendocrine tumors." (PMID 38098508, 2023).
tumor (continued). "The expression of all six FRGs was significantly different (p < 0.05), with FTH1, FTL, and PCBP1 being overexpressed in the tumor group and ZFP36, NCOA4, and TNF expressed less in the tumor group." (PMID 37555866, 2023). "This research led to the discovery of several new tumor-related genes, including AMIGO2, ZFP36, BTG1, and DLG5." (PMID 38275385, 2023). "Labelled by benign signatures, subclusters 1 and 2 similarly overexpressed metabolism‐related genes and tumour suppressors (KLF6, EGR1, GC, FAM46A, ZFP36, BTG2, etc.)." (PMID 35075805, 2022). "The promoter region of ZFP36 was bound by EGR3 and transcriptionally activated, thereby exerting a tumor-suppressive effect." (PMID 35538543, 2022). "The results of GEPIA showed that the expression levels of CCT6A and FAP were increased in the tumor tissues of GC patients, and the expression levels of ZFP36 and TP53I3 were decreased in the tumor tissues of GC patients." (PMID 36010886, 2022). "Further experiments have shown that ZFP36 can bind to PRC1 mRNA, thereby downregulating the expression of PRC1, inhibiting tumor growth, and promoting 5-Fu sensitivity." (PMID 34252149, 2021). "ZFP36 was shown to bind to the 3′UTR of PRC1 mRNA, thereby down-regulating PRC1 expression and exerting an anti-tumour effect." (PMID 34328175, 2021). "We and others have shown that ZFP36/TTP act as S/G2 and G2/M tumor suppressor, which become compromised in invasive breast cancer, and many cell cycle genes are upregulated in a post-transcriptional manner." (PMID 34535639, 2021). "Recently, it has also been suggested that miRNA-423 is capable of promoting tumor cell proliferation and migration by enhancing Wnt/CTNNB1 activity, thereby inducing ZFP36 down-regulation." (PMID 32784485, 2020). "RT-qPCR was used to detect the expression of LINC01600, JUND, ZFP36, and ATF3 in tumor tissues of 40 PCa patients collected in our hospital." (PMID 32318351, 2020). "Subsequently, ZFP36 expression in HCC cell lines was examined via qRT-PCR, and results demonstrated that the mRNA levels of ZFP36 were remarkably inhibited in HCC tumor tissues." (PMID 32602848, 2020). "Tristetraprolin (also known as TTP, TIS11, ZFP36, and Nup475) is a well-characterized tumor suppressor that is down-regulated in several tumor types." (PMID 26894969, 2016). "Moreover, in the absence of genomic loss, we provide evidence suggesting that ZFP36 downregulation in CRC is inversely correlated to Wnt/β-catenin constitutive activation, providing new insights into loss of post-transcriptional regulatory circuits during CRC tumour development and progression." (PMID 27463018, 2016). "Moreover, the ZFP36/PRC1 regulatory axis has been proposed as a potential therapeutic target, as restoring ZFP36 expression attenuates tumor proliferation and enhances chemosensitivity to agents such as 5-fluorouracil." (PMID 40361912, 2025). "Using 5 mM, 10 mM, and 20 mM metformin for 24 h, results indicated no changes in the ZFP36 protein induced by metformin in non-tumor cells." (PMID 39026155, 2024). "This article also defined AMIGO2, ZFP36, BTG1, and DLG5 tumor-related genes." (PMID 39114291, 2024). "Among the fourteen ferritinophagy-related genes studied, ten exhibited significant differences between tumor and normal samples: NCOA4, FTH1, FTL, SNCA (all p < 0.0001), BECN1 (p = 0.031), ELAVL1 (p = 0.00023), TNF (p = 0.00074), ATG16L1, ATG7, and ZFP36 (all p < 0.0001)." (PMID 39593730, 2024). "Taken together, this substantial evidence strongly confirms that these HMDRGs (ZFP36, SERPINE1, AKAP12, CAV1, and DUSP1) are strongly involved in hypoxia, mitochondrial dysfunction, and tumor immunity, in turn contributing to the modulation of GC pathogenesis and prognosis." (PMID 39165353, 2024). "ZFP36 expression before treatment did not correlate with the volume of post-treatment residual tumor (Spearman’s R value = –0.2187, P = 0.2)." (PMID 39560993, 2024).